RNU6-554P (RNA, U6 small nuclear 554, pseudogene)
Gene: Small nuclear RNA gene on chromosome 15 (43,602,543 to 43,602,648, forward strand). Ensembl gene ENSG00000222398.
Homologues: Orthologues: chimpanzee U6 (96% identical), dog U6 (78% identical), pig U6 (77% identical), pig U6 (76% identical), macaque U6 (68% identical). Paralogues in human: RNU6-353P (90% identical), RNU6-1060P (87% identical), RNU6-1011P (84% identical), RNU6-116P (84% identical), RNU6-132P (84% identical), RNU6-15P (84% identical), RNU6-19P (84% identical), RNU6-266P (84% identical), RNU6-31P (84% identical), RNU6-536P (84% identical), RNU6-558P (84% identical), RNU6-949P (84% identical), and 1286 more.